IL13 (interleukin 13)
Diseases named in the same sentence as IL13 in open-access papers (continued):
Sharing a sentence is not in itself a finding about the gene and the disease.
eosinophilia (continued). "Blockade of IL13 activity in mice after HDM sensitization reduces eosinophilia in BALF, peribronchial collagen, and goblet cell hyperplasia." (PMID 29272313, 2017). "TPL-2 deficiency led to exacerbated HDM-induced airway allergy, with increased airway and tissue eosinophilia, lung inflammation, and IL-4, IL-5, IL-13, and IgE production." (PMID 27484038, 2017). "In OVA-treated WT mice, PM2.5 exacerbated OVA-related lung eosinophilia along with an increase in Th2 cytokines (IL-5, and IL-13) and chemokines (eotaxin and MCP-3) and infiltration of eosinophils into the airways." (PMID 28887522, 2017). "Over-production of TH2-related cytokines (IL-4, IL-13, and IL-5) in IgG4-RD tissues has previously been reported and correlates with IgE and IgG4 class switch, blood eosinophilia, and eosinophilic infiltrates that are common features of IgG4-RD." (PMID 28348556, 2017). "Ongoing clinical trials will help to further dissect the contributions of IL-13 to tissue eosinophilia." (PMID 29034234, 2017). "Data from preclinical models and clinical trials of IL-13 inhibitors in patients have revealed mechanistic insights into the role of this cytokine in driving eosinophilia." (PMID 29034234, 2017). "Inflammation in AD is mediated by an initial Th2 phase, which is orchestrated by IL-4, IL-5, and IL-13 cytokines and is related to IgE production and eosinophilia." (PMID 28265582, 2017). "IVE and AET treatment also decreased IL-4 and IL-13 mRNA expression in lung tissue, as well as eosinophilia and IL-4, IL-5, and IL-13 production in BALF." (PMID 29062168, 2017). "In support of this idea, we found that supplementation of IPS-1−/− mice with exogenous IFNα reduced ILC2 numbers, airway eosinophilia and IL-13 production." (PMID 28539639, 2017). "Airway eosinophilia and the levels of IL-4, IL-5, and IL-13 were attenuated by the anti-CCL3 antibody." (PMID 27829417, 2016). "For example, similar to KB, oral exposure to live Lactobacillus reuteri bacteria can attenuate IL-5, IL-13 and eosinophilia in a mouse model of allergic airway inflammation, which was accompanied by a decrease in airway hyperresponsiveness." (PMID 27734946, 2016). "Both, upon OVA sensitization and challenge as well as IL-13 instillation, Socs1−/−MGLtg mice showed increased airway eosinophilia." (PMID 27917175, 2016). "It has been demonstrated that helminth infections strongly induce an immune response involving elevated Th2 cytokines (i.e., IL-4, IL-5, IL-9, and IL-13), IgE, IgA, eosinophilia, and mucus secretion." (PMID 27882241, 2016). "This corresponds with earlier findings on allergen-induced eosinophilia, which show that IL-5 promotes development and survival of eosinophils, whereas IL-13 mediates recruitment of eosinophils through secretion of eotaxins." (PMID 26965110, 2016). "For example, IL-13 induces tissue eosinophilia and high levels of IgE enhancing lung granuloma formation, whereas IL-13 blockage in mice was accompanied by changes in eosinophil accumulation and reduced granuloma size." (PMID 27648452, 2016). "In this study, FP significantly attenuated the LAR, AHR and Th2 pulmonary inflammation (IL-13, eosinophilia) in a dose-dependent manner." (PMID 25586266, 2015). "The aberrant immune response was accompanied with severe lung injury characterized with significant interstitial and alveolar inflammation, airway mucus production and eosinophilia, and IL13 expression in lung homogenates." (PMID 26231396, 2015). "IL-13, which shares a receptor component and signaling pathways with IL-4, plays a central role in airway eosinophilia and development of AHR." (PMID 25826377, 2015). "The production of IL-13 and tissue eosinophilia have been thought to participate in the fibrosis and resultant portal hypertension that causes morbidity during the chronic phase of the infection." (PMID 26448282, 2015). "IL13 additionally impacts upon tissue eosinophilia, tissue remodeling, and fibrosis, especially in the liver." (PMID 26693492, 2015).
eosinophilia (continued). "On the other hand, chronic expression of IFN-γ has also been shown to enhance allergen induced eosinophilia, IL-5, and IL-13 expression and has induced side effects when administered to allergic patients." (PMID 26557723, 2015). "The allergic reactions to OVA in mouse airway typically evoke TH2 dominated responses with dramatically increased levels of IL-4, IL-5, and IL-13, which are accompanied by eosinophilia and IgE expression." (PMID 24755955, 2014). "We showed here that mev mice had a spontaneous allergic rhinitis-like inflammation with eosinophilia, mucus metaplasia, up-regulation of Th2 cytokines (IL-4 and IL-13), chemokines (eotaxin), and MMPs." (PMID 25090641, 2014). "Airway eosinophilia induced by intratracheal IL-13 was feasibly suppressed by systemic treatment with glucocorticosteroid, while airway hyperresponsiveness and remodeling were resistant to glucocorticosteroid." (PMID 25344652, 2014). "Allergic inflammation is characterized by increased Th2 cytokines including IL-4, IL-5, and IL-13 resulting in tissue eosinophilia, epithelial mucus metaplasia, and IgE production." (PMID 24876829, 2013). "We have recently shown that BLT2 negatively regulates airway eosinophilia via suppressing the activation of IL-13-producing CD4+ T cell in OVA-sensitized/challenged mice." (PMID 23452625, 2013). "After mast cell reconstitution, eosinophilia and IL-13 in BALF were augmented by poly IC treatment even in KitW/KitW-v mice." (PMID 23452625, 2013). "While the Th2-type cytokine IL-13 can induce AHR independently of eosinophilia, ablation of eosinophils in a IL-5/eotaxin double knockout system abolishes AHR by reducing the ability of T cells to produce IL-13." (PMID 23378838, 2013). "Allosamidin and demethylallosamidin completely inhibited IL-13-induced eosinophilia and eotaxin at 10 and 1 mg/kg, respectively." (PMID 23765233, 2013). "The increased ILC2 expansion in IL-1β−/− mice correlated with increased early IL-5 and IL-13 cytokine production, helminth-induced eosinophilia and goblet cell hyperplasia." (PMID 23935505, 2013). "In the presence of poly IC, eosinophilia, IL-13 in BALF, and the numbers of IL-13-producing CD4+ and CD8+ T cells were augmented in Kit+/+ mice but not in KitW/KitW-v mice." (PMID 23452625, 2013). "The classic paradigm underlying allergic disease has been characterized by allergen specific Th2 cell production of IL-4, IL-5 and IL-13 leading to tissue eosinophilia, mucus production, and specific IgE production." (PMID 24876829, 2013). "IL-13 treatment induced eosinophilia counts and eotaxin concentration in bronchoalveolar lavage (BAL) fluid." (PMID 23765233, 2013). "Increased secretion of IL-4 and IL-13 by T cells leads to antibody class switching (from IgG to IgE) by B cells, and IL-5 induces eosinophilia." (PMID 23451048, 2013). "In animal models of allergic asthma, blockade of IL-13 markedly inhibits allergen-induced airway hyperresponsiveness, mucus production and eosinophilia." (PMID 22401596, 2012). "CF prevented the development of AHR, lung inflammation, and airway eosinophilia and decreased the level of Th2 cytokines (IL-5 and IL-13) in the BALF." (PMID 22439901, 2012). "OVA-induced mice showed eosinophilia, airway inflammation, mucus hypersecretion, and elevated levels of IL-4, IL-13 and eotaxin in BALF." (PMID 23110404, 2012). "The interstitial type of eosinophilia was consistent with the elevated levels of eotaxin and IL-13 in the BAL." (PMID 21896169, 2011). "We have previously shown this method to induce significant airway hyperresponsiveness to acetylcholine, increased serum IgE, increased eosinophilia and increased Th2 (IL-4, IL-5 and IL-13) cytokine expression." (PMID 22151973, 2011). "Eosinophilia is driven by allergen-activated Th2 cells that generate large amounts of Th2 cytokines (such as IL-4, IL-5, and IL-13)." (PMID 21772663, 2011).
eosinophilia (continued). "Prophylactic and therapeutic treatment with a high affinity, potent, neutralising anti-IL-13 mAb significantly inhibited HDM-induced airway eosinophilia, goblet cell upregulation and peribronchial collagen deposition." (PMID 20957211, 2010). "The immune response in clinically asymptomatic individuals is dominated by IL-4, IL-5, IL-10, and IL-13 secretion, IgE and IgG4 antibodies, and peripheral eosinophilia." (PMID 19381284, 2009). "As helminthiasis, atopy is the result of aberrant Th2 cytokine response to allergens, with an increased production of IL-4, IL-13, Il-9 and Il-5, with high amounts of allergen-specific and total IgE and eosinophilia." (PMID 19471606, 2008). "In animals, IL-33 treatment induces the expression of IL-4, IL-5 and IL-13 in the lung and intraperitoneal injection of IL-33 induces spleen eosinophilia." (PMID 18315837, 2008). "Alternatively, IL-10 or TGFβ support Th2 responses that impact on antibody production, mast cell degranulation and eosinophilia via secretion of IL-4, IL-5, IL-10, IL-13." (PMID 17430585, 2007). "In contrast, adult RSV infection prior to allergen exposure seemed to assert a "protective" response as evidenced by significantly decreased allergen induced pulmonary resistance, tissue eosinophilia, and IL-13 levels." (PMID 16893457, 2006). "Dupilumab blocks IL-4/IL-13 signaling, targeting key components of the type 2 (T2) inflammatory cascade: it reduces B-cell class switching toward IgE, suppresses effector T2 signals, and decreases tissue eosinophilia and other T2 markers." (PMID 41210306, 2025). "In this study, we found that this subgroup exhibited not only an increase in the levels of inflammatory cytokines, such as IL-6 but also a profile indicative of type 2 inflammation, including peripheral blood eosinophilia and elevated serum IL-4 and IL-13 levels." (PMID 40278124, 2025). "Finally, some authors have questioned the tapering of oral corticosteroids (OCS) as a potential contributor to blood eosinophilia observed during IL‐4/IL‐13 treatment." (PMID 40492692, 2025). "In contrast to mice treated with the control IgG antibody to SLPI KO mice, SLPI KO mice treated with anti-IL-33 neutralizing antibody showed reduced airway inflammation and fewer numbers of BAL total cells, ratio of eosinophilia, and Th2 cytokines (e.g., IL-5 and IL-13) in BAL fluid." (PMID 40546642, 2025). "Its superior performance likely stems from its dual inhibition of IL‐4 and IL‐13 signaling via IL‐4Rα blockade, a mechanism validated in preclinical models where IL‐4Rα knockout mice exhibited reduced mucosal eosinophilia and polyp burden in house dust mite‐induced nasal polyposis." (PMID 41178615, 2025). "Moreover, in addition to LPS, β-glucans contained in fine matter particles were suggested to exacerbate murine lung eosinophilia paralleled by increased IL-4 and IL-13 production in bronchoalveolar lavage fluid." (PMID 39337403, 2024). "Finally, in OVA-sensitized BALB/c mice, TLR2/6 intratracheal administration before OVA challenge significantly decreased BAL IL-5 and IL-13 but increased BAL eosinophilia." (PMID 39273551, 2024). "A Th2-skewing of T-bet-deficient CD4+ cells may also cause inflammation of the upper respiratory tract, peripheral eosinophilia, and an increase in Th2-cytokines IL-4, IL-5, and IL-13." (PMID 38835658, 2024). "The basis for atopy may stem from an exaggerated Th2 response involving cytokines such as IL-4, IL-5, and IL-13, as well as eosinophilia." (PMID 38742158, 2024). "In this scenario, IL-13 signals directly to biliary epithelial cells to induce cell proliferation and hyperplasia, and it independently signals to liver fibroblasts promoting liver fibrosis and eosinophilia." (PMID 38051583, 2024).
eosinophilia (continued). "When assassin lung cytokine modules, no overt Th2 cytokine module was observed in vaccinated and challenged mice exhibiting eosinophilia, a marked difference from small rodent models of VAERD which are characterized by high levels of IL-4, IL-5, and IL-13 and weight loss." (PMID 37600776, 2023). "In our study, the relative proportions of M2 compared to M1 macrophages in the upper airways of WT mice was highest during early infection and, in concordance with eosinophilia and expression of IL-13 in the lung, suggested a Th2 dominant phenotype that was absent in TLR7 KO mice." (PMID 37795093, 2023). "Furthermore, MID-1 siRNA ablated both eotaxin-1 expression and eosinophilia after rIL-13 administration, which indicative that IL-13 induces eosinophilic infiltration through MID-1 signaling." (PMID 38026128, 2023). "However, IL-33 administration can also induce marked type 2 inflammation, with eosinophilia, increased production of the interleukins IL-4, IL-5 and IL-13 as well as mucus production and epithelium remodeling." (PMID 35844529, 2022). "In addition, the Scnnlb transgenic juvenile mice exhibit type 2 airway inflammation such as IL-13, airway eosinophilia, and alternative macrophage activation with reduced mucociliary clearance." (PMID 34983467, 2022). "Expansion of ILC2s and activation by IL-33 from damaged parenchymal cells results in IL-13 production driving fibrotic gene expression in hepatic stellate cells in fibrosis models, or IL-5 production with resultant hepatic inflammation and eosinophilia in immune-mediated hepatitis models." (PMID 35359972, 2022). "Compared to RV-A (RV-1B) infection, RV-C (RV-C15) infection induced higher BALF eosinophilia, mRNA expression of IL-5, IL-13, IL-25, Muc5ac and Gob5/Clca, protein production of IL-5, IL-13, IL-25, IL-33 and TSLP, and expansion of ILC2 in naive and HDM-immunized BALB/c mice." (PMID 35386658, 2022). "Especially, IL‐5 contributes to eosinophilia, whereas IL‐13 is involved in mucus hypersecretion." (PMID 35344296, 2022). "Eosinophilia was accompanied by large increases in IL-13 and, especially, IL-5." (PMID 35699942, 2022). "The same treatment also significantly reduced the expression of genes linked to Th2 response and eosinophilia (Il4 and Il5 but not Il13) as well as eosinophil recruitment (Ccl5 and Ccl11) in Atg7fl/fl;Lyz2‐Cre ECRS mice." (PMID 35988262, 2022). "Furthermore, pharmacological inhibition of IL-6 during airway inflammation was associated with a marked local increase in protein levels of IL-13, IL-4, and IL-5, which are critically involved in Th2-mediated eosinophilia." (PMID 35408882, 2022). "Mice deficient in CD1d-/- and Jα18-/- iNKT cells showed a decrease in airway hyperresponsiveness and eosinophilia, while the adoptive transfer of IL-4- and IL-13-producing iNKT cells restored the airway inflammation, suggesting that type 2 iNKT cells are responsible for asthmatic inflammation." (PMID 35720287, 2022). "However, type 2 inflammation characterized by production of interleukin-4 (IL-4) and IL-13 in the lung, airway eosinophilia, and high levels of IgE antibodies occurs in ~50% of patients with asthma." (PMID 33976140, 2021). "However, several other inflammatory pathways have been shown to support eosinophilia, including IL-13, and most recently, the alarmin cytokines TSLP and IL-33." (PMID 33917396, 2021). "Given that insufficient NLRP1 exacerbated eosinophilia and IL-13 levels in the mouse model we studied, it is conceivable that blocking this axis with agents such as IL-4Rα may work more effectively in carriers of the NLRP1 M1184V variant." (PMID 33378691, 2021). "ILC2 activation and resultant Th2 cytokine release is now considered a key event in type 2 inflammatory diseases, with the production and release of IL-5 resulting in eosinophilia, IL-13 resulting in airway mucus production and remodeling, and IL-9 promoting goblet cell hyperplasia and mastocytosis." (PMID 33917396, 2021).
eosinophilia (continued). "However, several other inflammatory pathways have been shown to support eosinophilia, including IL-13, the alarmin cytokines TSLP and IL-33, and the IL-3/5/GM-CSF axis." (PMID 33917396, 2021). "Finally, we showed that i.n. challenge with recombinant human IL-4 or human IL-13 leads to eosinophilia, lung inflammation, and mucus production in hIL-4/hIL-13KI; hIL-4RαKI mice." (PMID 33976140, 2021). "In addition, the LRRC31 mRNA was positively correlated with eosinophilia and IL13 and IL5 expression, and was related to cellular immune regulation as well as inflammatory response." (PMID 34616724, 2021). "Notably, the eotaxin chemokines are markedly induced by IL-13, providing a synergistic mechanism by which Th2 cells and ILC2s, coproducing IL-5 and IL-13, regulate tissue eosinophilia." (PMID 34209213, 2021). "The production of type 2 cytokines (IL-4, IL-5, IL-10, and IL-13), as well as granulocyte-macrophage colony-stimulating factor (GM-CSF), by these cells induces eosinophilia, M2 macrophage polarization, and the secretion of immunoglobulin G1 (IgG1), IgG4, and IgE." (PMID 33013887, 2020). "In addition to IL-5, eosinophil recruitment and subsequent eosinophilia rely on ILC2 derived IL-13 and stroma derived eotaxin—an essential eosinophil chemokine." (PMID 32079296, 2020). "However, as with the primary infection, the induction of airway remodelling coincided with increased type-2 inflammation (IL-13 production, airway eosinophilia, mucus hypersecretion), which waned by 21 dpi." (PMID 32658914, 2020). "Since tissue eosinophilia is governed by the production of cytokines such as IL-5 and to a lesser extent by IL-13 and IL-4, it is assumed that eosinophilia either in the blood compartment or in the bronchi of asthmatic patients is a reflect of type 2 inflammation." (PMID 32296705, 2020). "In addition to ILC2, basophils, mast cells, and eosinophilia constitute IL-4– and IL-13–producing cells of the innate immune system during lung helminth infection." (PMID 33193446, 2020). "Evidence also exists supporting the proposition that exacerbated IL-13 level in BAL of OVA-challenged mice born to HFD-fed dams may contribute to their increased lung eosinophilia." (PMID 31805682, 2019). "IL-13 and eotaxin have been demonstrated to promote eosinophilia." (PMID 31889961, 2019). "The induction of eosinophilia and goblet cell metaplasia depends on IL‐5 and IL‐13, respectively." (PMID 29444897, 2018). "Nevertheless, IL-13 and IL-17 inhibition protected the animals from eosinophilia, mucus hyperplasia, and hyperresponsiveness of the airways and the elimination of neutrophilic inflammation, suggesting the effectiveness of combination therapies that control both Th2 and Th17 responses." (PMID 29379497, 2017). "IL-13 was secreted from these activated cells and improves airway obstruction and develops many of the asthmatic features including airways hyper-responsiveness, mucus hypersecretion, airway eosinophilia and B-cell activation (Tsitsionetal., 2012 ▶)." (PMID 27247924, 2016). "Recent studies have clearly defined the differential roles of IL-4 and IL-13 in allergic inflammation; IL-4 preferentially regulates Th2 cell function and IgE synthesis, whereas IL-13 mediates the pathophysiological processes that control mucus production, eosinophilia and AHR." (PMID 26740570, 2016). "An effect of parasite colonisation on RSV disease would seem to be via different mechanisms, since Th2-driven immunopathology (as observed in allergic inflammation), shares many of the features of anti-helminth parasite immune responses (e.g. eosinophilia, production of IgE, IL-13 and eotaxin)." (PMID 27560829, 2016). "In KSpn-mediated suppression of AAD we identified important suppressive roles for: TLR2 in eosinophil infiltration into the airways (partial) and AHR; TLR4 in eosinophilia of the airways and blood, IL-5 and IL-13 release from splenocytes and AHR, and; MyD88 in airway and blood eosinophilia and AHR." (PMID 27309732, 2016).